ESPL1 (extra spindle pole bodies like 1, separase)
Diseases named in the same sentence as ESPL1 in open-access papers (continued):
Sharing a sentence is not in itself a finding about the gene and the disease.
tumor (continued). "The strong correlations observed suggest that ESPL1 may act synergistically with these genes within the same oncogenic pathways, promoting uncontrolled proliferation and tumor progression in BC." (PMID 41268575, 2025). "Thus, ESPL1 emerges as a promising marker of aggressive tumor growth and potential therapeutic vulnerability in hormone receptor-negative breast cancers." (PMID 41268575, 2025). "Furthermore, ESPL1 expression was analyzed in an equal number of normal and tumor samples (n = 114 each), and the results confirmed significantly higher ESPL1 expression in tumor tissues." (PMID 41268575, 2025). "Moreover, using the UALCAN database, we evaluated ESPL1 expression across pathological stages and found it to be significantly upregulated in tumor samples across all stages compared to normal tissue." (PMID 41268575, 2025). "Previous studies have shown that ESPL1 is highly expressed in various tumours." (PMID 38813236, 2024). "Although previous studies had repeatedly explored the elevated expression of ESPL1 in various tumours, this was the first time that the epigenetic regulatory mechanisms of ESPL1 have been analysed using histone modification and three-dimensional genomics with the results being reported." (PMID 38813236, 2024). "Furthermore, GDSC and CTRP, two of the largest tumor-related drug databases, were utilized to discover drugs that target tumors with high ESPL1 expression." (PMID 37006282, 2023). "Notably, the study found that interference with ESPL1 expression significantly inhibited the proliferation of tumor cells." (PMID 37006282, 2023). "Furthermore, the study revealed that tumors with high ESPL1 expression tended to be more heterogeneous based on various tumor heterogeneity indicators." (PMID 37006282, 2023). "However, the tumor stage was negatively correlated with the expression of ESPL1, a phenomenon that deserves further study." (PMID 37006282, 2023). "Current studies indicated that ESPL1 may also participate in the formation and progression of the tumor." (PMID 36359523, 2022). "Therefore, we conducted GSEA analysis to determine whether ESPL1 is involved in tumor-related signaling pathways." (PMID 34512713, 2021). "However, upon observation of mice maintained in our colony beyond the time period shown in survival curve, we found that the ESPL1+/hyp animals had a longer mean average tumor-free lifespan (more than 800 days vs. 600 days for WT) compared to that reported for WT C57Bl/6 animals." (PMID 21799785, 2011). "Specifically, overexpression of ESPL1 and MCM5 has been significantly correlated with advanced tumor stages and disease progression, underscoring their potential utility as biomarkers for predicting clinical outcomes." (PMID 41226409, 2025). "The expression levels of KIF2C, CENPA, CDC20, UBE2C, ESPL1, KIF23, and PLK1 were significantly higher in the tumor tissues of patients with a HOST-response compared to those without a HOST-response." (PMID 39201599, 2024). "Results suggested that higher expression of ESPL1 was significantly correlated with higher clinical stage, TNM stage, gender, age, residual tumor, smoker, OS event, and DSS event in patients with LUAD." (PMID 35814478, 2022). "Results showed that four of these hub proteins (AURKA, CDC45, ESPL1, and RAD54L) were over-expressed in all tumor subtypes." (PMID 32932728, 2020). "There were 15 genes, including ESPL1 and MCM5, that showed relativity (P < 0.05) with tumor stage changing." (PMID 29884122, 2018). "Finally, we used the ssGSEA method to determine the correlations between ESPL1, AURKB, BUB3, and FAM83D and 24 types of tumor-infiltrating immune cells." (PMID 35646670, 2022). "Moreover, we detected that the expression of ESPL1 and MCM5 were negatively correlated with tumor stage progression." (PMID 29884122, 2018).
tumor (continued). "In our study, we found that ESPL1 was upregulated in LUAD and LUSC, and clinical feature analysis suggested that higher expression of ESPL1 was significantly correlated with higher clinical stage, TNM stage, gender, age, residual tumor, smoker, OS event, and DSS event in patients with LUAD." (PMID 35814478, 2022). "In addition, ESPL1 and MCM5 expression were negatively correlated with tumor stage progression, and regression analysis indicated that ESPL1 and MCM5 were correlated to tumor stages (Pearson correlation = − 0.25713; P = 9.54E-05 and Pearson correlation = − 0.13982; P = 0.023, respectively)." (PMID 29884122, 2018). "In previous studies, ESPL1 expression in LUAD was positively correlated with the level of infiltration of Th2 cells and negatively correlated with the level of infiltration of mast cells, iDCs, DCs and CD8T cells and might be involved in immune evasion and tumour migration." (PMID 38813236, 2024). "Furthermore, epigenetic modifications and microRNAs (miRNAs) could potentially influence tumour suppression and growth by affecting gene expression; however, the roles that these factors potentially play in the upstream regulation of ESPL1 have not been clarified." (PMID 38813236, 2024).
infection (7 papers, 2009 to 2024). The state of being infected such as from the introduction of a foreign agent such as serum, vaccine, antigenic substance or organism. "Among the highly upregulated genes in both infection groups were ESPL1, DOCK8, ARID3A, PFKFB4, ANKZF1, BANP and GRB7, all of which exhibited a log2 fold change of ≥1.5." (PMID 37193047, 2022).
ESPL1 also shares sentences with these, for which no sentence is quoted: colon carcinoma (2 papers); esophageal carcinoma (2); non-small cell and small cell lung cancer (2); Pan (2); shigellosis (2); small cell lung carcinoma (2); adenocarcinoma (1); B- cell lymphomas (1); COVID-19 (1); diarrheal disease (1); head and neck cancer (1); hemolytic-uremic syndrome (1); Hepatitis (1); large cell carcinoma (1); liposarcoma (1); lung squamous cell carcinoma (1); migraine (1); neuroblastoma (1); pancreatic cancer (1); pituitary adenoma (1); pyelonephritis (1); tongue cancer (1); triple-negative breast carcinoma (1).